CAPRIN1 (cell cycle associated protein 1)
Diseases named in the same sentence as CAPRIN1 in open-access papers (continued):
Sharing a sentence is not in itself a finding about the gene and the disease.
tumor (continued). "IHC analysis of paraffin-embedded tissues revealed that the positive expression of caprin-1 was significantly lower in GC tissues compared with that in the adjacent non-tumor tissues [23.33% (21/90) vs. 66.67% (20/30)]." (PMID 30687106, 2018). "Caprin-1 mRNA and protein levels were significantly lower in the GC tissues than in those in the adjacent non-tumor tissues (P < 0.01)." (PMID 30687106, 2018). "TRK-950 binds to human CAPRIN-1 with high affinity and can strongly induce tumor cell death through fragment crystallizable-mediated effector functions, including antibody-dependent cell-mediated cytotoxicity and antibody-dependent cell-mediated phagocytosis (ADCP)." (PMID 40557916, 2025). "Interestingly, 70% of the tumor cells in this patient were identified as CAPRIN-1 at a strong intensity (3+)." (PMID 40557916, 2025). "Furthermore, we found that higher level of STK38 indicated poor prognosis in our dataset and TCGA database, suggesting that Caprin-1 promotes tumor growth through ULK1/STK38-dependent autophagy." (PMID 38082307, 2023). "Our work reveals that Caprin-1-induced autophagy and immune activation influence PDAC progression and targeting Caprin-1 may play crucial roles against tumor development." (PMID 38082307, 2023). "Collectively, caprin-1 and circIPO7 have opposite effects on cell proliferation, and circIPO7 may serve as a tumor suppressor by binding caprin-1." (PMID 36732659, 2023). "These suggest Caprin-1 as a crucial regulator for tumor growth." (PMID 38082307, 2023). "Finally, to further investigate the impact of Caprin-1 on tumor growth in vivo, the subcutaneous xenograft tumor model was established in nude mice using Caprin-1 knockdown (shCaprin-1) or the control cells (shCtrl)." (PMID 36855123, 2023). "Moreover, subcutaneous injection of the caprin-1-silenced MKN-45 cells in nude mice significantly suppressed tumor formation and the growth rate compared to those in the control group." (PMID 36732659, 2023). "In vitro and in vivo assays showed that Caprin-1 knockdown affected ESCA tumor growth." (PMID 36855123, 2023). "These indicate that Caprin-1 may promote tumor growth through immune modulation and inflammatory-related pathways." (PMID 38082307, 2023). "The results of the present study corroborated those of previous reports and showed that Caprin-1 expression had a significantly positive association with 18F-FDG PET parameters, which can reflect the glucose metabolism and growth patterns of tumor cells in ESCA patients." (PMID 36855123, 2023). "Furthermore, data analysis of NPC microarray gene expression data showed that CAPRIN1 was significantly highly expressed in tumor tissue in two NPC gene microarray datasets (GSE12452 and GSE53819)." (PMID 36515758, 2022). "Moreover, we verified through colony formation experiments that the sensitivity of tumor cells to X-ray irradiation increased after CAPRIN1 knockdown in NPC cells." (PMID 36515758, 2022). "In addition, CAPRIN1 is highly expressed when tumor cells adapt the adverse conditions, thereby promoting chemoresistance." (PMID 35571493, 2022). "It has been proved that AKAP1, SNAI1 and Caprin1 could be target genes of miR-199a-5p, and their overexpression worsens tumor developments." (PMID 35517408, 2022). "The overexpression of caprin-1 may contribute to the growth and invasion of several types of tumor cells." (PMID 34376192, 2021). "Moreover, knockout of Caprin1 in C4–2 cells significantly reduced the growth of tumor xenografts in mouse models." (PMID 31771591, 2019). "In addition, xenograft tumor model was constructed to verify the phenotypes upon CAPRIN1 silencing." (PMID 36855123, 2023). "Overall, these results demonstrated that Caprin-1 silencing could inhibit tumor growth in vivo." (PMID 36855123, 2023).
tumor (continued). "In addition, mice inoculated with Caprin-1High tumor increased serum Caprin-1 levels." (PMID 38082307, 2023). "The oncogenic mechanisms of CAPRIN1 might relate to cell cycle regulation in tumor cells." (PMID 36515758, 2022). "In contrast, sh-CAPRIN1 treatment significantly increased CD8 + T cells and decreased Treg cells in the tumor tissue." (PMID 40819077, 2025). "Caprin-1 activated autophagy through the interaction with ULK1 and STK38 that promoted tumor growth." (PMID 38082307, 2023). "When identical numbers of CAPRIN-1high and CAPRIN-1low (low CAPRIN-1 membrane expression) cells were implanted into NOD-SCID (NOD.CB17-Prkdcscid/NcrCrl) mice, CAPRIN-1high cells resulted in much faster tumor growth." (PMID 37082579, 2023). "CAPRIN-1 and USP10 not only have opposite effect on SGs regulation, but also have opposed incidence on cell proliferation and tumor development." (PMID 32882814, 2020). "Taken together, our findings established a tumor suppressive role for miR-1 in the progression of ccRCC by targeting CDK4, CDK6, Caprin1 and Slug and suggested miR-1 can be served as a novel potential therapeutic target for ccRCC." (PMID 26036633, 2015). "In the fresh subcutaneous tumor, we detected the expression of miR-1 by RT-PCR and the expression of CDK4, CDK6, Caprin1 and Slug by Western Blot." (PMID 26036633, 2015). "Besides, CAPRIN1 knockdown inhibits ESCC cell proliferation and tumour growth and decreased the expression of METTL3 and WTAP." (PMID 36855123, 2023). "CAPRIN-1 enhances proliferation, whereas USP10 inhibits tumor progression and invasion." (PMID 32882814, 2020). "Besides, Caprin-1 recruits TAMs and blockade of Caprin-1 may hamper TAM-induced immunosuppressive effects and enhance anti-tumor response." (PMID 38082307, 2023).
infection (5 papers, 2014 to 2025). The state of being infected such as from the introduction of a foreign agent such as serum, vaccine, antigenic substance or organism. "Since G3BP1, G3BP2 and CAPRIN1 had previously been determined to be critical regulators of stress granules (SG) assembly, another aspect of the cellular response to infection, we examined SG formation in infected cells and upon IFN treatment." (PMID 24992036, 2014). "During the early stages of infection, the viral factory is surrounded by the rough endoplasmic reticulum, which attracts essential translation initiation factors, including G3BP1 and Caprin-1." (PMID 40733530, 2025). "Of note, CAPRIN1 interacts with ATG16L1 and G3BP1 in uninfected cells, and they are relocalized to MNV RC upon infection." (PMID 37052473, 2023). "In order to investigate a link between IFN-mediated antiviral activity and that of G3BP1, G3BP2 and CAPRIN1, cells depleted of these three proteins were pretreated with IFN-β before infection with DENV-2 NGC." (PMID 24992036, 2014). "Taken together, these data indicate that G3BP1, G3BP2 and CAPRIN1 interact with DENV-2 gRNA and sfRNA during infection." (PMID 24992036, 2014). "Interestingly, the SL-I of ZIKV can interact with proteins related to stress granules, such as Caprin-1, G3BP1, G3BP2 and USP10, to assess the success of infection." (PMID 36982407, 2023). "To further test this hypothesis and determine the importance of this mechanism during infection and for viral evasion of the IFN response, we constructed mutant DENV-2 replicons unable to sequester G3BP1, G3BP2 and CAPRIN1." (PMID 24992036, 2014).
neurodevelopmental disorder (3 papers, 2022 to 2026). A behavioral and cognitive disorder with onset during the developmental period that involves impaired or aberrant development of intellectual, motor, or social functions. "This minor effect on SGs is further supported by identification of a neurodevelopmental disorder associated Caprin-1-I373K mutation, causing only minor effects on SG/cell phenotype despite disrupted Caprin-1 recruitment." (PMID 37161291, 2023).
head and neck tumors (1 paper, 2022). "Moreover, the analysis of TCGA-HNSC RNA-Seq data showed that CAPRIN1 was consistently upregulated in head and neck tumors." (PMID 36515758, 2022).
hematologic cancer (1 paper, 2023). "And we did not detect CAPRIN-1 surface expression in a comprehensive set of established hematologic cancer cell lines, although we detected CAPRIN-1 in the cell lysates of both normal and hematologic cancer cells by Western blot analysis." (PMID 37082579, 2023).
respiratory disease (1 paper, 2021). "The CAPRIN1 gene was previously enriched for bovine respiratory disease; however, studies reporting associations for this gene in cattle are scarce." (PMID 35052358, 2021).
CAPRIN1 also shares sentences with these, for which no sentence is quoted: Intellectual disability (2 papers); neurodegenerative disease (2); respiratory failure (2); age-related hearing loss (1); amyotrophic lateral sclerosis (1); Anxiety (1); Asperger’s syndrome (1); bladder cancer (1); cerebellar ataxia (1); cervical cancer (1); COVID-19 (1); depression (1); developmental delay (1); Epileptic encephalopathy (1); glioblastoma (1); melanoma (1); memory impairment (1); prostate tumor (1); speech delay (1); triple-negative breast carcinoma (1); ZIKV infection (1).